IL2 (interleukin 2)
Diseases named in the same sentence as IL2 in open-access papers (continued):
Sharing a sentence is not in itself a finding about the gene and the disease.
infection (continued). "Concentrations of IL-2, IFN-γ, and TNF-α rapidly increased in the early stage of infection and reached to a peak within the first week." (PMID 28445973, 2017). "The expression levels of IL-2, IL-4, IL-6 and TNF-α in calcitriol-treated infected mice were significantly lower than the untreated infected mice on 2 days post-infection (p <0.01)." (PMID 28114957, 2017). "Patients in the earliest stage of infection (ill ≤ 4 days) had significantly higher IFN-γ, IL-12p70, and IL-2 concentrations (all adjusted p ≤ 0.048)." (PMID 28628633, 2017). "After challenge with B. microti, the levels of cytokines including IL-17, IL-4, IL-6, IL-10, IL-12p70, G-CSF, IFN-γ, TNF-α, IL-2, GM-CSF, MCP-1, MIP-1α, MIP-1β, and MIP-2 in the serum of the BMSA vaccinated group changed as infection progressed." (PMID 29312230, 2017). "TCM cells can express IL-2, multiply quickly and turn into effector T cells when they encounter the antigen again, whereas TEM cells are located in infection sites and can express IFN-γ very rapidly." (PMID 27566581, 2016). "Intracellular cytokine staining paralleled these findings as infection of DCs with EBOV significantly reduced percentages of T cells positive for activation markers IFNγ, IL2 or TNFα, as well as for the marker of degranulation CD107α+." (PMID 27930745, 2016). "Processes related to cytoskeletal remodeling and cellular junctions, as well as inflammatory responses (IL-2, IL-5, IL-18, CCL2, TNF, IFN, and TGF-β signaling) were also upregulated following infection with C. concisus BAA-1457." (PMID 27677841, 2016). "IL-2/6/β and IFN-β were significantly upregulated at two instances during the infection process, but the ranges of upregulation were different." (PMID 27846843, 2016). "Cytokines typical of the immune response (IL-1β, IL-2, IFN-γ, IL-4, IL-17A) were analyzed at 2 and 28 days after infection." (PMID 27189736, 2016). "Early after infection, many of the ESAT6-specific CD4+ T cells were polyfunctional based on their production of IL-2, IFNγ, and TNF." (PMID 26967901, 2016). "As previously detected in naturally infected cattle, experimental infection-elicited polyfunctional responses biased toward IFN-γ/TNF-α and IFN-γ/TNF-α/IL-2 profiles." (PMID 27799930, 2016). "Infection with EBOV/VP35m infection resulted in a significant increase, as compared to wt EBOV, in proliferating CD4+ cells secreting IFNγ, TNFα and IL-2." (PMID 27930745, 2016). "Rapid and more-sustained elevations in IL-1ra, MIP-1α, IL-5, IL-10 and IL-17 levels were followed by IL-1β, IL-2, IL-7, IL-9, IL-12, IL-15, IFN-α2, MIP-1β, FGF-2 and GM-CSF at over 2 months post-infection, and accompanied by the recovery of CD4+ cells." (PMID 27830756, 2016). "This revealed 13 mediators of inflammation that correlated with infection status, which were, in order of strength of significance, IL-4, IL-5, IL-7, IL-15, IFN-α, IL-12, IFN-γ, IL-17, IL-1Ra, TNF-α, IL-1β, IL-10, and IL-2." (PMID 27418744, 2016). "Due to infection of macrophages with AG83+Sias, reduction of the genetic expression of Th1 cytokine genes (IFNγ and IL-2) and upregulation of Th2 cytokine genes (IL-4, IL-10 and TGFβ) were observed." (PMID 27494323, 2016). "Six hours after infection, gene changes involved pathways such as HMGB-1, interleukin (IL)-2, IL-6, IL-8, janus kinase/signal tranducer and activator of transcription (JAK/STAT), interferon, and ERK 5 signaling (P < 0.01)." (PMID 27119120, 2016). "There was a significant increase at day 7 relative to day 5 post-infection in abundance of interleukins (IL) including IL1B, IL2, IL4, IL5, IL6, IL10 and IL13." (PMID 27311020, 2016). "Previous findings on the dominance of IL-2+ IFN-γ+ and IL-2+ IFN-γ- secreting cells in immune-controlled infection states of M. tuberculosis, e." (PMID 25785445, 2015).
infection (continued). "In this study, primers for quantitative real time PCR for Saimiri IFNγ, TNFα, IL2, IL6, IL10, and IL12 were validated and used in a study of splenic responses in S. sciureus during blood infection by P. falciparum." (PMID 25890318, 2015). "When purified PHA/IL-2 stimulated CD4+ T-cells are infected with cell free GFP reporter viruses in vitro, infected GFP+ cells are fully visible within 2 days after infection." (PMID 26055104, 2015). "CCR6 is also one of the characteristics for a specific population of memory cells that secrete TNF-α, IL-2, and IFN-γ upon infection." (PMID 25894562, 2015). "Antiretroviral therapy promotes significant increases of IL-2+IFN-γ+- and IL-2+TNF-α+- secreting CD4+ T cells and hinders the progression from infection to active TB, while single IFN-γ+ CD4+ T cells declined significantly." (PMID 25822536, 2015). "CD4 Th1 immunity is critical to sustain residual CD8 T-cell activity to control infection during persistent infection and is characterized in CD4 T cells by the secretion of IFN-γ, TNF-α, and IL-2." (PMID 26322025, 2015). "Serum concentration profiles (mean ± SD) for IL-2 and IL-10 cytokines in weeks 18 and 22 from E. multilocularis-infected mice treated with ABZ-CS-MPs or ABZ-T (75 mg/kg) and control, infection control groups." (PMID 26352932, 2015). "In contrast, at day 14 after infection, increased levels of the pro-inflammatory cytokines TNF-γ, IFN-γ, IL-2, IL-6, and IL-17 were observed in mice that had received a high inoculum dose relative to mice that had received medium and low doses." (PMID 25889515, 2015). "TGF-β suppressed the expression of the high affinity IL-2Rα chain CD25, which restricted IL-2 signaling via STAT5 and mTOR in Tfh progenitor cells early during infection in vivo." (PMID 25569154, 2015). "Increased expression of chicken IL-2 during virulent NDV replication in naïve chickens decreased viral titers in blood, spleens, oral and cloacal secretions on day 4–5 post infection." (PMID 26253150, 2015). "Based upon the presence of IL-2 and IFN-γ throughout B. microti infection in mouse models, it is likely that, during the initial stages of infection, establishment, and progression, a Th1 response predominates." (PMID 26697208, 2015). "IL-2 and IFN-γ are present approximately a week after infection and peak around day 12 during the progression stage." (PMID 26697208, 2015). "On the other hand, T cells play a critical role in this link by secreting IL2, which empowers CD56+ cells to productively respond to a number of stimuli during infection." (PMID 25706946, 2015). "For the trans-infection assays, we limited MDDC exposure to virus to 1 hour, before washing and co-culturing with autologous PHA, IL-2 stimulated CD4+ T-cells." (PMID 25809903, 2015). "Specifically, significant IL-2 production at the beginning of infection (p<0.0001, ANOVA, week 6) began to wane as infection became chronic, when the IL-2 levels became indistinguishable from the treated animals." (PMID 25996375, 2015). "On week 9 after infection, significant differences between treatments in the total frequencies of TNF-α (p = 0.0077) and IL-2-producing-CD4+ T cells of the spleens (p = 0.0035) were found." (PMID 24966857, 2014). "Following infection or injury, increased PGE2 is reported to influence the immune response by several mechanisms, including the inhibition of Th1 cytokines IL-2, IL-12 and IFN-γ; impairing phagocytosis and lymphocyte proliferation." (PMID 25153081, 2014). "While IL-2 and IL-17 expression by MLNC Foxp3+ Treg cells was very low in both genotypes of naive mice, infection induced a significant increase in Foxp3+IL-17+ cell numbers in the BALB/c strain." (PMID 24185641, 2014). "In our study, we found that immunization with pcDNA-mGMCSF-Pxn1 induced the highest frequency of IFN-γ+TNF-α+IL-2+ CD4+ T cells and showed the highest level of protection of mice from L. major challenge infection." (PMID 25500571, 2014).
infection (continued). "All immunized groups receiving either of liposomal rCPA, rCPB and rCPC singly or as cocktail produced significant upregulation of IL-2 and IFN-γ mRNAs in comparison to controls, which progressively increased at 2 and 3 months post infection." (PMID 25144181, 2014). "In the early infection, the CD4+ T cell can release IFN-γ, IL-2, and TNF-α, which can activate macrophages to fight against M. tuberculosis." (PMID 24741595, 2014). "IAV infection significantly increased the levels of all tested proinflammatory cytokines (IL-1β, IL-6, IL-2, TNF-α, IFN-α, IFN-β and IFN-γ) in lung homogenates between 1.2- and 13.7-fold relative to the baseline (before infection)." (PMID 24865588, 2014). "Statistically significant increases in total percentages of CD4+IFNγ+, CD4+IL-2+, and CD4+TNFα+ T cells were detected post-infection relative to D0 (P<0.05, 0.01, and 0.05, respectively) following primary infection." (PMID 25397604, 2014). "Our data demonstrate a consistent pattern of pro-inflammatory cytokine production by C. jejuni-specific CD4+ T cells following primary infection, which included IFNγ, TNF-α, IL-2, and the chemokine, MIP-1β." (PMID 25397604, 2014). "We also observed remarkable increases in IL-1β, IL-2, IL-10 and TNF-α at 7 dpi after which IL-1β and IL-2 dropped to pre-infection levels, IL-10 and TNF-α decreased to lower levels than pre-infection levels." (PMID 24465897, 2014). "In this study, expression levels of IL-4, IL-10, IL-13 and TNF-α were significantly up-regulated while the expression levels of IL-1β,IL-18,IFN-γ, IL-2, IL-15, IL-17F, IFN-α, IFN-β, IL-3 and CSF-1 were markedly decreased in PBMCs at all stages of infection." (PMID 24358317, 2013). "Treg cells can also be generated in the presence of interleukin (IL)-2 and transforming growth factor (TGF)-β or as induced (i)Treg cells in response to infection by microorganisms." (PMID 23776551, 2013). "The cellular responses to a culture filtrate protein of Mtb however is generally a slowly evolving one and gradually builds up (IL-2, IL-5, IFN-γ and TNF-α) over the course of infection with M. ulcerans (right column)." (PMID 23516649, 2013). "Both Il2 (GFP) and Il21 (mCherry) were predominantly expressed by CD4+ compared to CD8+ T cells and frequencies increased from days 7–15 post infection with low dose LCMV-WE." (PMID 23696736, 2013). "In the group with M. leprae infected macrophages co-cultured with PBMCs, the concentrations of IL-2, IL-1β and TNF-α peaked on day 1 after infection and then declined gradually." (PMID 23782413, 2013). "On the other hand, IL-2 and IL-4 levels in TNF-α KO mice were significantly higher than those of WT and IL-10 KO mice during mock infection and following JaOArS982 infections." (PMID 23940775, 2013). "IL2 demonstrated the greatest level of gene expression induction in response to all three LPAIV infections, especially during infection with CK/MD/MinhMa (19.7 fold up-regulation)." (PMID 23521892, 2013). "When MYA-1 T-cells were supplemented with IL-2, productive FIV infection was inhibited by Prostratin." (PMID 23201205, 2013). "The decreased levels of IL-2, IL-15, IFNα, IFNβ and IFN-γ indicated that infection of REV-A suppressed Th1-type immune response." (PMID 24358317, 2013). "In the presence of IL-2, FIV replicated in the MYA-1 T-cells, with the FIV capsid protein (p24) level in the supernatant reaching a plateau six days post infection." (PMID 23201205, 2013). "In contrast, in mice vaccinated with adjuvanted recombinant H28 alone (H28/H28) we observed the highest production of IL-2 per single cell and the highest frequency of antigen specific TNF-α/IL-2 expressing CD4 T cells pre and post infection." (PMID 23977248, 2013). "Based on our findings in the mouse model we suggest that a protective vaccine against infection with M.tb should primarily possess the ability to induce (and maintain) CD4 phenotypes expressing TNF-α/IL-2." (PMID 23977248, 2013).
infection (continued). "Our data also showed a correlation between the amounts of triple positive IL-2+TNFα+IFNγ+ vaccine-specific CD4 T cells induced by immunization and the subsequent level of protection against infection with M.tb." (PMID 22768165, 2012). "However, this pathogen may uses other mechanisms to circumvent host-cell defenses and establish infection by dowregulating other adaptive immune response genes such as IL-2 and IL-4 and delaying the apoptotic death of neutrophils through activation of the Jak-STAT pathway." (PMID 22935149, 2012). "In our infection model, PD-1high CD8 T cells produced less pro-inflammatory cytokines IL-2, IFN-γ and TNF-α in response to ex-vivo stimulation with immunodominant SSIEFARL peptide as compared to the PD-1medium CD8 T cell pool." (PMID 22808056, 2012). "Inflammation is the first response of the immune system to infection or irritation; inflammation is mediated by cytokines such as TNF-α, IL-1β, IL-2, IL-6, and PGE2." (PMID 22919407, 2012). "In contrast to the response to NC infection, IFN-γ-secreting cells were consistently more frequent than IL-2-secreting cells in DR1 mice after PR8 infection." (PMID 22457834, 2012). "In our study, we demonstrated that stimuli that mimic infection (LPS, SEB or PMA) or pro-inflammatory mediators, as TNF-α or IL-2 or IL-15, induce the cell surface expression of HMGB1 and its secretion at 48 h or 14 days after treatment, respectively." (PMID 21915243, 2011). "PBMC from patients homozygous for SAMHD1 R164X as well as WT SAMHD1 were stimulated with interleukin 2 (IL-2) and PHA followed by subsequent infection with the replication-competent CCR5-tropic HIV-1 SF162." (PMID 22174685, 2011). "Therefore, we investigated whether various activation signals, such as proinflammatory stimuli (TNF-α or IL-2 or IL-15), or signals that mimic infection (LPS, SEB or PMA), influence the cell surface expression and active secretion of HMGB1 by human cord blood cells." (PMID 21915243, 2011). "In fact, there was down-regulation of genes involved in innate immune response like IL2, IL15 and STAT1 at early stages (4 and 8 hpi) of infection." (PMID 21439068, 2011). "It was observed that there is a significant induction of IL-2 in CXCL-10-/- than in WT, at day 2 (~40%,) and 4 (~80%, p < 0.05) post-infection." (PMID 21439091, 2011). "Patients with PB disease present very low bacterial counts, exhibiting localized infection and lesions characterized by expression of type 1 (TH1) T helper lymphocyte-related cytokines (cell-mediated immunity) as IL-2, IL-6, IL-12, IFN-γ, and TNF." (PMID 22220182, 2011). "Intracellular expression of cytokines TNF-α, IL-2, and IFN-γ was determined in popliteal lymph node CD4+ and CD8+ T cells during acute FIV infection in controland CD25 depleted cats." (PMID 21364928, 2011). "Nef, which is expressed early after infection in resting T cells, increases the number of T cells that activate NFAT and NF-κB promoter elements, secrete IL-2, and express activation markers such as CD25 and CD69 in response to TCR stimulation." (PMID 21819585, 2011). "In contrast, demyelination was not detectable after infection of the mice with wild-type (wt) HSV-1 alone or infection of the mice with the HSV-IL-4 or HSV-IFN-γ viruses, which are identical to HSV-IL-2 except that they express IL-4 or IFN-γ instead of IL-2." (PMID 21364747, 2011). "We next performed an infection of PHA and IL-2 activated PBMCs and treated these cells with various concentrations of alsterpaullone for up to 18 days." (PMID 20334651, 2010). "We analyzed the levels of IL-2, IL-4, IL-5, IL-10, IL-12(p70), GM-CSF, IFN-γ and TNF-α in the culture supernatant of macrophages 24 h post infection." (PMID 19680450, 2009). "qRT-PCR was performed for detecting IL-2 mRNA expression using cDNA from control and JEV infected NSPCs at different time points of infection, from 1 dpi to 4 dpi." (PMID 19956550, 2009).
infection (continued). "We thus next examined the levels of TNF, IL-1β, IL-2, IL-6, IL-10, and MCP-1 (also known as CCL2) in human PBMC infected by CDC1551, HN878, and HN878 pks1-15::hyg 2 and 4 days post-MTb infection." (PMID 19568431, 2009). "Cells from infected lungs, taken at week 6 or week 43 post infection, were stimulated with TB10.4 3–11 or TB10.4 74–88 prior to staining with anti-CD4, -CD8, -IFN-γ, -TNF-α and –IL-2." (PMID 19529765, 2009). "The functional profile of T cells specific for these peptides is characteristic of an infection with long term stimulation of the immune system, with high levels of IFN-γ-secreting T cells and low levels of IL-2 production." (PMID 18846233, 2008). "PBMCs isolated from a healthy donor were stimulated with IL-2 and PHA-L for 72 hours and, after washing, were then similarly treated upon infection by the HTLV-I gp46-pseudotyped virions." (PMID 19032754, 2008). "Expression of IL-2 and IL-12 cytokines in Raji cells transduced at a relatively low MOI of 200 was transient, peaked between 1 and 3 days post-infection, and was detectable up to 10 days." (PMID 15485577, 2004). "TNF-α, IL-2, IL-4, IL-10, and IL-12p70 were not produced at 4 h post-infection with any of the bacterial strains, in either HT-29 or Caco2 cell lines (data not shown)." (PMID 41459941, 2026). "The proportion of IL-2 and IFN-γ secreted by CD4+CD44+ and CD8+CD44+ T cells in the vaccine immunization group exhibited a significant increase compared to the PBS + infection and CpG + infection group." (PMID 40266142, 2025). "IL-2 and its receptor are important in the proliferation and differentiation of CD4+ lymphocytes, specifically of naïve to helper T-cell subtypes following infection." (PMID 41148718, 2025). "However, as the infection duration prolongs, IFN-γ, IL-2, and TNF-β significantly decrease (p < 0.05), while IL-5 significantly increases (p < 0.05), indicating that Th2-type humoral immunity becomes the main anti-parasitic mechanism." (PMID 40979361, 2025). "In addition, J774A.1 macrophages were infected with H37Rv (multiplicity of infection [MOI] = 5), and the mRNA expression of cytokines TNF-α, IL-2, IL-12, and IFNγ was detected, which was consistent with the results of LPS treatment." (PMID 40396746, 2025). "An adaptive response driven by T-helper 1 lymphocytes (Th1) triggers an effective immune reaction that helps manage the infection by promoting the production of proinflammatory cytokines such as interferon-gamma (IFN-γ), interleukin-2 (IL-2), and tumor necrosis factor-alpha (TNF-α)." (PMID 41310729, 2025). "In the CsCP3-immunized group, expression levels of IFN-γ, IL-2, IL-4, and IL-10 rose rapidly post-infection but subsequently dropped to levels not significantly different from the control by the second or fourth week." (PMID 40248698, 2025). "Given the critical role of IL‐2 and IFN‐γ in anti‐infective immunity, their elevation may indicate enhanced resistance to infection, while increased IL‐4 may reflect modulation of inflammation." (PMID 41190418, 2025). "Prior evidence from our group and others shows that pre-existing IL-2-secreting T cells from prior endemic human coronavirus infection can cross-recognize SARS-CoV-2 and may protect against infection despite exposure." (PMID 40472803, 2025). "Different from immunosuppressants and biologics which often increased infection incidence, low-dose IL-2 treatment is effective in SLE without increased infection incidence." (PMID 40337274, 2025). "In dTHP-1 cells, the rM.semg/Rv3717 strain infection resulted in a 2.80-fold increase in P62 expression, while LC3II/I ratio, IL-2 expression and iNOS expression decreased by 0.58-fold, 0.59-fold, and 0.47-fold, respectively, compared to the rM.semg infection group." (PMID 41154817, 2025).